HOTAIR (HOX transcript antisense RNA)
Diseases named in the same sentence as HOTAIR in open-access papers (continued):
Sharing a sentence is not in itself a finding about the gene and the disease.
glioma (continued). "Further studies indicated that the tumorigenic actions of HOTAIR in gliomas additionally rely on its ability to suppress programmed cell death protein 4 (PDCD4) in a PRC2-dependent manner." (PMID 38366205, 2024). "HOTAIR's capability to act as a molecular sponge and repress a plethora of target miRNAs adds another facet to its pro-tumourigenic roles in glioma pathology." (PMID 38682637, 2024). "These predictions were confirmed experimentally using an in vivo rodent model with glioblastoma xenograft, wherein the authors also observed robust anti-glioma effects of strategies to knockdown HOTAIR expression." (PMID 38366205, 2024). "Experimental data from A172 glioma cells identified miR-148b-3p as yet another direct mediator of HOTAIR signaling in gliomas." (PMID 38366205, 2024). "The in vitro and in vivo inhibition of HOTAIR function blocked the expression of PD-L1 on the surface of glioma cells, promoting the infiltration of tumour-related immune cells." (PMID 38887279, 2024). "In these cells, PD-L1 is positively regulated by HOTAIR and its activation can alter T cell toxicity through the NF-κB signalling pathway promoting inflammatory signalling and immune escape in glioma cells." (PMID 38887279, 2024). "Another recently discovered sponging target of HOTAIR with relevance for gliomas is miR-219, as confirmed by siRNA-mediated silencing of HOTAIR in U87 cells." (PMID 38366205, 2024). "Bioactive phytochemicals, such as schisandrin B (Sch B) derived from the medicinal plant Schisandra chinensis, have also been proposed to elicit significant anti-glioma repressive actions against HOTAIR sponging of miR-125a-mTOR signaling." (PMID 38366205, 2024). "Relevances of HOTAIR as a prognostic marker and therapeutic target in gliomas and other brain cancers are discussed in detail." (PMID 38366205, 2024). "Data from both human glioma tissues and U251 and U87 cells indicate that HOTAIR is responsible for trans-silencing of miR-141." (PMID 38366205, 2024). "For example, MALAT1, HOTAIR, and H19 have been found to promote glioma cell proliferation, migration, invasion, and angiogenesis, thereby acting as oncogenes." (PMID 37444408, 2023). "HOTAIR is over-expressed in many cancers, including breast and prostate carcinomas, and adult glioma, and the level of expression of HOTAIR determines to some degree the extent of LSD1/PRC2 binding." (PMID 35406676, 2022). "Specifically, we observed that the expression of the lncRNA HOTAIR, which plays a critical oncogenic role in malignant glioma, was restricted to IDHwt glioma samples." (PMID 35563134, 2022). "HOTAIR has numerous targets in glioma, such as PRC2 complex, miR‐326, miR‐141, miR‐125a, and miR‐148b‐3p." (PMID 35592755, 2022). "In the present study, we successfully radiolabeled antisense oligonucleotide probe targeting LncRNA HOTAIR to track the expression of HOTAIR in glioma cells." (PMID 35042456, 2022). "Gliomas with poor prognosis have higher HOTAIR expression, and HOTAIR expression is also higher in classical or mesenchymal subtypes." (PMID 35592755, 2022). "A study of the therapeutic effect of Schisandrin B on glioma found that the HOTAIR–miR‐125a–mammalian target of rapamycin (mTOR) pathway plays a key role in proliferation and invasion outcomes." (PMID 35592755, 2022). "Circulatory biomarker: Serum HOTAIR levels were significantly higher in glioblastoma patients than controls and correlated with HOTAIR expression within the glioblastoma tissue and glioma grade." (PMID 34322395, 2021). "To verify the regulatory mechanism of the HOTAIR gene on the occurrence and progression of glioma, we heat-mapped approximately 2600 genes negatively related to HOTAIR expression." (PMID 34082742, 2021). "Another tumor suppressor miRNA involved in HOTAIR regulation during glioma progression is miR-14, frequently downregulated in glioma tissue samples and cells." (PMID 33540611, 2021).
glioma (continued). "Our results suggest that HOTAIR can negatively regulate the expression of PPARα and that the combination of fenofibrate and si-HOTAIR treatment can significantly inhibit the progression of gliomas." (PMID 34082742, 2021). "High expression of HOTAIR was found to interact with miR-148b-3p and inhibit malignancy in glioma cell." (PMID 33980320, 2021). "Our study not only explores the molecular mechanism by which HOTAIR regulates PPARα but also verifies the therapeutic effect of the combined application of the PPARα agonist fenofibrate and siRNA HOTAIR on glioma through in vivo animal experiments." (PMID 34082742, 2021). "The anticancer effect of I-BET151 in glioma is achieved, at least in part, by downregulating HOTAIR." (PMID 34540687, 2021). "An abnormally high expression of the lncRNA HOTAIR has been previously demonstrated in glioma cells." (PMID 34887871, 2021). "Suppressing HOTAIR expression, together with mimics of miR-326, strongly inhibited glioma cell proliferation, migration and invasion." (PMID 34316694, 2021). "Epigenetic modulators such as BRD4 (member of BET‐bromodomain and extra terminal domain) proteins with histone acetyltransferase and chromatin remodeling functions upregulate HOTAIR expression in glioma cells." (PMID 34316694, 2021). "The expression of HOTAIR was positively correlated with the messenchymal subtype of glioma, but negatively correlated with the subtype of proneural." (PMID 34887871, 2021). "HOTAIR expression induction in in vivo model of glioma upregulated β-catenin, while its silencing inhibited glioma cell migration/invasion." (PMID 34576322, 2021). "For the first time, it was shown that after knockdown of the expression of HOTAIR in gliomas, the expression of PPARα was significantly upregulated, and the invasion and proliferation ability of gliomas were obviously inhibited." (PMID 34082742, 2021). "We have previously demonstrated that HOTAIR is a positive factor in the progression of malignant glioma and is directly related to poor prognosis in glioma patients." (PMID 34887871, 2021). "An analysis of clinical samples found abnormal HOTAIR expression in stromal glioblastoma, which was correlated with the malignancy degree of the glioma." (PMID 34887871, 2021). "A proteomics analysis showed that in HOTAIR knockdown glioma cells, 1074 proteins were up-regulated, whereas 390 proteins were inhibited." (PMID 34887871, 2021). "For example, GAS5 and HOTAIR were dysregulated in gliomas and related to the proliferation, migration, invasion and chemosensitivity of glioma cells 28, 35-37." (PMID 34659533, 2021). "Existing studies have shown that lncRNA HOTAIR as a ceRNA ‘sponged’ miR-126-5p and promotes glutamine metabolism in glioma." (PMID 33849550, 2021). "The experimental results showed that the high expression of HOTAIR promoted the enrichment of H3K27me3 protein in the PPARΑ promoter region, while reducing the expression of HOTAIR in glioma cell lines reduced the amount of binding." (PMID 34082742, 2021). "To elucidate HOTAIR’s effects, we analyzed different databases and datasets including samples from glioma cell lines and clinical glioma samples." (PMID 34887871, 2021). "Theoretically, there are numerous lncRNAs, such as HOTAIR, H19 and NEAT1, that can be applied as diagnostic and prognostic indicators of glioma." (PMID 34178684, 2021). "To study the role of HOTAIR in gliomas, we transfected U87 and U251 glioma cells with si-HOTAIR lentivirus." (PMID 34082742, 2021). "Here, we report that HOTAIR is an activator lncRNA of the NF-κB pathway and demonstrate that its apparent upregulation promotes inflammatory signaling and immune escape in glioma cells." (PMID 34887871, 2021). "We knocked down HOTAIR in glioma cells by siRNA with SILAC labeling, and then total protein was extracted for proteome mass spectrometry." (PMID 34887871, 2021). "Metabolism: HOTAIR regulated glutamine metabolism, which is essential for glioma progression, by sponging miR-126-5p." (PMID 34322395, 2021).
glioma (continued). "lncRNA HOTAIR can be conveyed into endothelial cells via exosomes secreted by glioma cells, and HOTAIR is known to promote angiogenesis." (PMID 34616851, 2021). "Glioma malignancy is also promoted by HOTAIR via its interactions with the polycomb repressive complex 2 (PRC2) and certain miRNAs." (PMID 33980320, 2021). "HOTAIR is the target of miR-326 and its silencing promotes their tumor-suppressive effects on glioma cell lines." (PMID 34576322, 2021). "Both overexpression of miR-141 and knockdown of HOTAIR in a mouse model of human glioma resulted in significant reduction of tumor growth in vivo." (PMID 34576322, 2021). "HOTAIR expression correlated with glioma molecular subtype and was preferentially expressed in the classical and mesenchymal subtypes compared with the neural and proneural subtypes." (PMID 34576322, 2021). "In our previous studies, HOTAIR was considered not only an important marker of tumor classification and prognosis but also an important marker of glioma molecular subtypes." (PMID 34082742, 2021). "Bioinformatics analysis was used to elucidate the relationship between HOTAIR and NF-κB pathway in HOTAIR knockdown glioma cells." (PMID 34887871, 2021). "Microarray mRNA datasets, in which HOTAIR was overexpressed for 6 h or 48 h in U87 glioma cells, exhibited 1920 upregulated and 470 downregulated genes at both timepoints." (PMID 34887871, 2021). "By comparing the expression levels of HOTAIR and PPARα in low-grade gliomas and glioblastomas, it was found that the expression of HOTAIR in GBM was upregulated, while PPARα was expressed at low levels." (PMID 34082742, 2021). "HOTAIR also regulates glutaminase levels to enhance glioma progression via binding of miR-126-5p as a ceRNA." (PMID 33980320, 2021). "HOTAIR expression is commonly altered in glioblastoma and is especially abnormally elevated in mesenchymal glioma." (PMID 34887871, 2021). "Taken together, these findings indicate that the inhibition of HOTAIR function blocks the expression of PD-L1 to a certain extent on the surface of glioma cells, thereby further promotes the infiltration of tumor-related immune cells." (PMID 34887871, 2021). "The combination of AQB and palbociclib inhibitors has a more pronounced suppression effect on the cell cycle, especially gliomas with high expression of HOTAIR and EZH2 and low expression of CWF19L1." (PMID 32508030, 2020). "Several HOTAIR-dependent interferences in miR pathways have also been described in glioma, HCC prostate cancer and squamous cell carcinomas." (PMID 33375038, 2020). "In the present study, the in vitro experiments revealed the efficacy and mechanism of action AQB in combination with palbociclib on cell cycle inhibition in glioma cell lines, with a high expression of HOTAIR and EZH2, and a low expression of CWF19L1." (PMID 32508030, 2020). "HOTAIR was also identified through molecular subtyping in glioma, with higher expression in the mesenchymal and classical subtypes than in the neural and proneural subtypes, and as an independent prognostic factor in patients with glioblastoma." (PMID 32650527, 2020). "We proved that PTCSC3 as a formerly characterized tumor suppressor in thyroid cancer and glioma was likely an upstream inhibitor of HOTAIR, and the inhibition of HOTAIR by PTCSC3 is involved in the regulation of LSCC cell proliferation." (PMID 31171714, 2019). "To further explore the relevance of DNA methylation in HOTAIR regulation, we treated glioma cell lines with the global DNA demethylating agent 5-Aza-2′-deoxycytidine (5-Aza) followed by methylation-specific PCR (MSP) and quantitative PCR (qPCR) analyses." (PMID 29644006, 2018). "Here, we explore the multi-layered complexity of HOTAIR activation by integrating molecular (genetic and epigenetic) analyses, in silico approaches, and data from glioma patients and cell lines." (PMID 29644006, 2018).
glioma (continued). "Together, these data suggest that HOTAIR is highly expressed in high-grade gliomas, being particularly frequent in IDH-wt cases." (PMID 29644006, 2018). "In glioma, HOTAIR was reported to be involved in proliferation, invasion, cell cycle and colony formation ability, in vivo tumor growth, and GBM patients’ OS." (PMID 29644006, 2018). "Here, we evaluated the molecular alterations and upstream regulatory mechanisms of HOTAIR in glioma, the most common primary brain tumors, and its clinical relevance." (PMID 29644006, 2018). "HOTAIR gene expression, methylation, copy-number and prognostic value were investigated in human gliomas integrating data from online datasets and our cohorts." (PMID 29644006, 2018). "In this regard, recent studies have demonstrated that lncRNAs in gliomas can serve as molecular decoys, which move proteins or RNAs away from a specific location, like a “sponge” to miRNAs (e.g., HOTAIR/miR-326, CASC2/miR-21, XIST/miR-152, and Gas5/miR-222)." (PMID 28293170, 2017). "Introduction of the HOTAIR 5’ domain in human glioma-derived astrocytoma induced the expression of β-cantenin, resulting in elevated invasion/migration." (PMID 29088865, 2017). "For example, a well-characterized lncRNA, HOTAIR, contributes to the chemoresistance of lung adenocarcinoma and glioma via inhibiting p21 expression." (PMID 28831025, 2017). "The lncRNA HOTAIR is identified as an oncogene in GBM; by interacting with polycomb repressive complex 2 (PRC2), HOTAIR is positively associated with glioma staging, poor prognosis and the molecular subtype of glioma." (PMID 28187439, 2017). "The correlation of low miR-141 expression with high HOTAIR expression in human glioma patients is consistent with our finding that overexpression of miR-141 can downregulate HOTAIR in glioma cells." (PMID 27121316, 2016). "MiR-141–mediated regulation of HOTAIR expression in U87 and U251 glioma cells was further verified by HOTAIR mRNA expression analysis using qRT-PCR." (PMID 27121316, 2016). "A total of 56 glioma tissues were analyzed for the expression levels of HOTAIR mRNAs and for miR-141 expression by qRT-PCR." (PMID 27121316, 2016). "To investigate the miRNA-related functions of HOTAIR in glioma, we chose miR-141 as a model miRNA for further studies, with a particular focus on the target gene SKA2." (PMID 27121316, 2016). "We demonstrated that miR-141 mimic suppressed the clone formation of glioma cells while HOTAIR reversed the decrease in clone formation." (PMID 27121316, 2016). "In conclusion, our findings from the present study strongly suggest the involvement of HOTAIR in abnormal expression of miR-141 mediated by epigenetic modification targeted SKA2 in glioma." (PMID 27121316, 2016). "The present work provides specific epigenetic regulatory network between methylation, miRNA, and lncRNA, suggesting a novel strategy for the prevention and treatment of gliomas based on targeting miR-141 and its downstream HOTAIR." (PMID 27121316, 2016). "HOTAIR mRNA expression was markedly decreased by transfection of miR-141 mimic, and was upregulated by transfecting miR-141 inhibitor in U87 and U251 glioma cells." (PMID 27121316, 2016). "Current research indicates that HOTAIR is a negative prognostic factor for survival of patients with breast and colon cancer and glioma, and increased HOTAIR expression in patients has been correlated with increased metastasis." (PMID 25823657, 2015). "The expression levels of HOTAIR in human glioma tissues and cell lines were analyzed by real-time PCR." (PMID 26183397, 2015). "In glioma, HOTAIR expression can be activated in c-Myc targeted transcription, which has been shown to drive tumor progression while suppressing miRNA-130a expression." (PMID 26230711, 2015). "Despite mounting evidence suggesting the oncogenic role of HOTAIR in glioma, the mechanisms by which it regulates gene expression is incompletely understood." (PMID 26230711, 2015).
glioma (continued). "Further, HOTAIR was confirmed to be the target of miR-326 and miR-326 mediated the tumor-suppressive effects of HOTAIR knockdown on glioma cell lines." (PMID 26183397, 2015). "HOTAIR was found to be highly upregulated in GBM cells compared with control, and glioma cell growth was significantly reduced following depletion of HOTAIR transcript." (PMID 26230711, 2015). "In the present study, we aimed to investigate the expression and function of HOTAIR in human glioma cells." (PMID 26183397, 2015). "Our previous studies showed that HOTAIR is overexpressed in high-grade glioma patients, and its upregulation is predictive of poor prognosis." (PMID 25428914, 2015). "Our previous research indicated that HOTAIR promoted malignant progression and poor prognosis in glioma patients and exhibited pro-oncogenic activity." (PMID 25823657, 2015). "Here, we elucidated the function and the possible molecular mechanisms of lncRNA HOTAIR in human glioma U87 and U251 cell lines." (PMID 26183397, 2015). "Although the interaction between miR-326 and HOTAIR was confirmed, the biological behaviors of glioma cell regulated by miR-326 and HOTAIR need to be well confirmed." (PMID 26183397, 2015). "The level of HOTAIR expression in GBM was higher than in other low grade gliomas and normal brain tissues (P < 0.05)." (PMID 25823657, 2015). "To identify putative HOTAIR target genes, we performed microarray analysis of 220 Chinese glioma samples." (PMID 25428914, 2015). "We also found that the expression of the 5′ domain of HOTAIR partially rescues the cell cycle arrest induced by HOTAIR knock-down in glioma cells." (PMID 25428914, 2015). "In this study, we demonstrated that HOTAIR was highly expressed in the glioma tissues and cell lines." (PMID 26183397, 2015). "In conclusion, HOTAIR promotes cell cycle progression in glioma as a result of the binding of its 5′ domain to the PRC2 complex." (PMID 25428914, 2015). "Recent report has indicated that HOTAIR primarily serves as a prognostic factor for glioma patient survival, a biomarker for identifying glioma molecular subtypes, as well as a critical regulator of cell cycle progression." (PMID 26183397, 2015). "Quantitative RT-PCR demonstrated that HOTAIR expression was up-regulated in glioma tissues and cell lines." (PMID 26183397, 2015). "In conclusion, our study revealed that knockdown of HOTAIR inhibited the proliferation, cell migration and invasion, and promoted apoptosis and cell cycle arrest by up-regulating miR-326 in human glioma cells." (PMID 26183397, 2015). "HOTAIR has been identified as a potential biomarker for glioma subtypes and tumor grades, with its silencing in glioblastoma cell lines (LN229 and U87) shown to disrupt cell cycle regulation by downregulating E2F1, cyclins, CDKs while upregulating inhibitors p16 and p21." (PMID 40004468, 2025). "In addition, by performing K-M curve analysis, the expression of H19, HOTAIR, miR-148a-3p, miR-222-3p, MBP and HMGA2 had a significant association with glioma patients’ survival." (PMID 40351420, 2025). "HOTAIR plays an important role in tumor growth, especially in glioma." (PMID 40821785, 2025). "Understanding the regulatory mechanisms of the HOTAIR/miR-126/GLS axis in gliomas could promote novel treatments for this disease." (PMID 39539540, 2024). "Indeed, exposure of serum-derived extracellular vesicles from glioblastoma subjects containing high abundances of HOTAIR was found to robustly facilitate glioma cell proliferation, invasiveness, and temozolomide resistance both in vitro and in vivo." (PMID 38366205, 2024). "In conclusion, these data suggest that HOTAIR expression may be a relevant and potent prognosticator of glioma progression, severity, and grade type, either alone or in combination with other biomarkers." (PMID 38366205, 2024). "Thus, increases in the levels of HOTAIR in glioma tissues and in vitro tumor cells have been found to be associated with reduced expression of miR-326." (PMID 38366205, 2024).